COQ7 (coenzyme Q7, hydroxylase)
Description:
Catalyzes the hydroxylation of the 5-methoxy-2-methyl-3-(all-trans-polyprenyl)benzoquinone at the C6 position and participates in the biosynthesis of ubiquinone (Probable). Catalyzes the reaction through a substrate-mediated reduction pathway, whereby NADH shuttles electrons to 5-methoxy-2-methyl-3-(all-trans-decaprenyl)benzoquinone, which then transfers the electrons to the two Fe(3+) centers. The binding of 5-methoxy-2-methyl-3-(all-trans-polyprenyl)benzoquinone (DMQn) mediates reduction of the diiron center by nicotinamide adenine dinucleotide (NADH) and initiates oxygen activation for subsequent DMQ hydroxylation. The physiological substrates are 5-methoxy-2-methyl-3-(all-trans-nonaprenyl)benzoquinone (DMQ(9)) and 5-methoxy-2-methyl-3-(all-trans-decaprenyl)benzoquinone (DMQ(10)), however in vitro the enzyme does not have any specificity concerning the length of the polyprenyl tail, and accepts tails of various lengths with similar efficiency. Also has a structural role in the COQ enzyme complex, stabilizing other COQ polypeptides. Involved in lifespan determination in a ubiquinone-independent manner (By similarity). Plays a role in modulating mitochondrial stress responses, acting in the nucleus, perhaps via regulating gene expression, independent of its characterized mitochondrial function in ubiquinone biosynthesis.
Synonyms: CLK-1; CAT5; COQ10D8; HMNR9
Tractability: Small molecule: a structure with a bound ligand is known. Antibody: UniProt places it where antibodies can reach, with medium confidence; the Human Protein Atlas places it where antibodies can reach. PROTAC: ubiquitination databases record sites on it; its protein half-life has been measured.
Target class: Enzyme; Oxidoreductase
Gene: Protein-coding gene on chromosome 16 (19,067,614 to 19,080,095, forward strand). Ensembl gene ENSG00000167186.
Subcellular location: Mitochondrion inner membrane; Mitochondrion; Nucleus; Chromosome
Subcellular location (Human Protein Atlas): Plasma membrane; Nucleoplasm
Pathways (Reactome):
Metabolism: Ubiquinol biosynthesis
Gene Ontology:
Molecular function: 3-demethoxyubiquinone 3-hydroxylase (NADH) activity; protein binding; monooxygenase activity; oxidoreductase activity, acting on paired donors, with incorporation or reduction of molecular oxygen, NAD(P)H as one donor, and incorporation of one atom of oxygen
Biological process: ubiquinone biosynthetic process; determination of adult lifespan; regulation of reactive oxygen species metabolic process; response to xenobiotic stimulus
Cellular component: chromosome; mitochondrial inner membrane; mitochondrion; nucleus; ubiquinone biosynthesis complex; extrinsic component of mitochondrial inner membrane
Genetic constraint (gnomAD): Loss-of-function variants: 19 observed, 22.35 expected, observed/expected ratio (o/e) 0.85, 90% interval 0.59 to 1.25. The upper end of that interval is the gene's LOEUF score, 1.25, which puts it in group 5 of 6, group 1 being the genes least tolerant of losing a copy. Missense variants: 281 observed, 284.68 expected, observed/expected ratio (o/e) 0.99, 90% interval 0.89 to 1.09. Synonymous variants: 119 observed, 112.33 expected, observed/expected ratio (o/e) 1.06, 90% interval 0.91 to 1.23.
Gene-disease validity (ClinGen):
ClinGen rates the evidence that COQ7 causes each of these diseases.
distal hereditary motor neuropathy (autosomal recessive): Strong.
Homologues: Orthologues: pig COQ7 (86% identical), guinea pig COQ7 (86% identical), chimpanzee COQ7 (85% identical), rat Coq7 (82% identical), macaque COQ7 (81% identical), mouse Coq7 (80% identical), rabbit COQ7 (73% identical), dog COQ7 (69% identical), tropical clawed frog coq7 (66% identical), zebrafish coq7 (61% identical), Drosophila melanogaster Coq7 (51% identical), Caenorhabditis elegans clk-1 (47% identical).
Diseases named in the same sentence as COQ7 in open-access papers:
COQ7 is named in the same sentence as 34 diseases in open-access papers, as found by Europe PMC text mining. Sharing a sentence is not in itself a finding about the gene and the disease. The quoted sentences say what the papers report.
Encephalopathy (3 papers, 2022 to 2024). Encephalopathy is a term that means brain disease, damage, or malfunction. "COQ7 pathogenetic variants cause primary CoQ10 deficiency and a clinical phenotype of encephalopathy, peripheral neuropathy, or multisystemic disorder." (PMID 38702428, 2024). "Moreover, the spectrum of symptoms of encephalopathy, intellectual disability, seizures, and muscle involvement has been described in patients with variants responsible for other primary coenzyme Q10 deficiency (COQ2, COQ4, COQ6, COQ7, COQ9) as well as in patients with COQ8A-ataxia." (PMID 36295857, 2022).
astrocytomas (1 paper, 2022). "Taken together, we have demonstrated that lower CoQ10 levels and protein levels of COQ3, COQ5, COQ6, COQ7, COQ8A, and COQ9 were associated with higher tumor grades and lower CS activity or COX II level in human astrocytomas." (PMID 35204836, 2022). "The levels of COQ3, COQ5, COQ6, COQ7, COQ8A, and COQ9, but not of COQ4, were lower in Grade IV astrocytoma tissues than in controls or low-grade (Grades I and II) astrocytomas, but PDSS2 levels were higher in astrocytoma tissues than in controls." (PMID 35204836, 2022).
cardiac hypertrophy (1 paper, 2022). "A large number of genes (at least 19) related to mitochondria or energy production, such as Oma1 and COQ7, were found to have genetic interactions with ATE1 through GO term studies, and those partial proteins have been reported to be involved in the regulation of cardiac hypertrophy." (PMID 35341136, 2022).
developmental delay (1 paper, 2022). "These defects lead to a developmental delay that can be completely restored by feeding with CoQ or the headgroup precursor diHB that bypasses Coq7 function." (PMID 36229432, 2022).
diabetes (1 paper, 2013). "The remaining 3 decreased diaphragm carbohydrate metabolism genes, Dcxr, Pfkfb1 and Coq7, were not significantly changed in any previous diabetes studies." (PMID 24199937, 2013).
distal hereditary motor neuropathy (1 paper, 2024). "CoQ10 has demonstrated protective properties against vincristine-induced peripheral neuropathy and assists in managing COQ7 gene mutation-associated distal hereditary motor neuropathy." (PMID 39464795, 2024).
heart failure (1 paper, 2023). Inability of the heart to pump blood at an adequate rate to meet tissue metabolic requirements. "In summary, our results provide mechanistic information about the roles of previously studied genes namely, NDUFS4, LRPPRC, and COQ7, in heart failure." (PMID 37276142, 2023).
hypertrophic cardiomyopathy (1 paper, 2024). A condition in which the myocardium is hypertrophied without an obvious cause. "Here, we report novel compound heterozygous variants in the COQ7 gene responsible for a prenatal onset (20 weeks of gestation) of hypertrophic cardiomyopathy and intestinal dysmotility in a Bangladesh consanguineous family with two affected siblings." (PMID 38702428, 2024). "Here, we report for the first time a fetal imaging study demonstrating a dysmorphic profile, cardiomegaly biventricular hypertrophic cardiomyopathy, and intestinal hyperechogenicity at the 20thweek of gestation as first disease signs in a family with COQ7 gene defect." (PMID 38702428, 2024).
Insulin resistance (1 paper, 2018). Increased resistance towards insulin, that is, diminished effectiveness of insulin in reducing blood glucose levels. "Similarly, siRNA knock down of the key regulatory proteins in CoQ biosynthesis that were down-regulated in insulin-resistant mouse and human adipose tissue (Coq7 or Coq9) lowered mitochondrial CoQ9 and triggered insulin resistance." (PMID 29402381, 2018). "In the present study, we found that the protein levels, but not the corresponding levels of the mRNAs, of the CoQ biosynthetic enzymes COQ7 and COQ9 were decreased in insulin resistance." (PMID 29402381, 2018).
Leukoencephalopathy (1 paper, 2023). This term describes abnormality of the white matter of the cerebrum resulting from damage to the myelin sheaths of nerve cells. "Another brain pathology observed in individuals with COQ defects is disturbed myelination and leukoencephalopathy (PDSS1, COQ2, COQ6, COQ7 and HPDL)." (PMID 36978966, 2023).
Mitochondrial myopathy (1 paper, 2015). "In contrast, in the new Coq9Q95X mouse model reported here, the lack of COQ9 protein results in decreased levels of only COQ7 and COQ5 proteins, which leads to moderate CoQ deficiency and a mild mitochondrial myopathy, especially evident in females." (PMID 25802402, 2015).
prostate carcinoma (1 paper, 2024). A carcinoma that arises from epithelial cells of the prostate gland. "COQ7 is involved in ubiquinone biosynthesis, but its role in prostate cancer has not been studied yet." (PMID 38173042, 2024).
sensorineural hearing loss (1 paper, 2022). "Mutations in the human COQ7 gene are associated with primary CoQ10 deficiency and are further associated with several disease states, predominantly hypertonia and sensorineural hearing loss (SNHL)." (PMID 36552517, 2022).
tumor (4 papers, 2019 to 2024). "We similarly identified certain molecules such as alpha‐aminoadipic semialdehyde synthase (AASS) and coenzyme Q 7 homolog ubiquinone (COQ7) whose functions were unknown in tumor cells." (PMID 31025554, 2019).
COQ7 also shares sentences with these, for which no sentence is quoted: encephalomyopathy (2 papers); peripheral neuropathy (2); amyotrophic lateral sclerosis (1); Ataxia (1); autosomal recessive dHMN (1); cancer (1); cardiomyopathy (1); Duchenne muscular dystrophy (1); Friedreich ataxia (1); Gastrointestinal obstruction (1); hereditary optic neuropathy (1); Hypertension (1); Intellectual disability (1); Kidney stones (1); lactic acidosis (1); Leigh syndrome (1); Nephropathy (1); primary coenzyme Q10 deficiency (1); Pseudoxanthoma elasticum (1); respiratory failure (1).